CD48 (CD48 molecule)
Diseases named in the same sentence as CD48 in open-access papers (continued):
Sharing a sentence is not in itself a finding about the gene and the disease.
tumor (continued). "Here we show that the expression of the Signaling Lymphocyte Activation Molecule (SLAM) family members CD48 and Ly9 (CD229) by MHC-I-deficient tumor cells significantly contributes to NK cell activation." (PMID 27054584, 2016). "When NK cells develop in the presence of T cells or B cells that lack inhibitory MHC-I but express activating CD48 and Ly9 ligands, the NK cells’ ability to respond to MHC-I-deficient tumor cells is severely compromised." (PMID 27054584, 2016). "The majority of GFP+ tumor cells expressed CD48 (99.3±0.7%), CD47 (89.5±6.9%) and Mac1 (74.4±14.7%), while expression of Gr1 (4.73±2.65%), B220 (1.35±1.52%), CD4 (18.6±16.8%), and Ter119 (3.13±1.6%) was low or absent." (PMID 22952867, 2012). "Reduced CD48 expression by tumor cells may impair CD244-CD48 interactions, rendering them less recognizable by natural killer (NK) cells and cytotoxic T lymphocytes (CTLs)." (PMID 40610562, 2025). "This suggests that overexpression of CD48 may suppress the activity of mDCs, monocytes, and neutrophils, enabling tumor cells to evade immune surveillance." (PMID 40963634, 2025). "Furthermore, NK cells expanded via the engagement of the SLAMF2/CD48-SLAMF4/CD244 axis showed stronger anti-tumor capability and infiltration ability into the tumor microenvironment, leading to an improvement in therapeutic efficiency." (PMID 38612827, 2024). "Although healthy cells also express CD48 on their surface, we suspect that the expression of CD48 by these cells does not reach a threshold to efficiently recruit the seYTS and elicit a sufficient activation to harm these cells in contrast to a CD48-positive tumor." (PMID 37609636, 2023). "The HO1-high group exhibited suppressed CD48 levels in tumor cells relative to the HO1-low group." (PMID 36058936, 2022). "Notably, cis interaction between 2B4 and CD48 on NK cells has been reported to reduce the availability of 2B4 to interact with CD48 in trans on tumor cells, resulting in a heightened NK cell activation threshold." (PMID 34149719, 2021). "Interfering with the cis interaction therefore enhanced the lysis of CD48-expressing tumour cells." (PMID 27249817, 2016). "However, we found that CD48 expression was decreased in Tregs from metastatic tumor tissues, suggesting that although the proportion of Tregs increased, their immunosuppressive capacity may be diminished in the metastatic tumor microenvironment." (PMID 40963634, 2025). "In addition, using the TCGA cancer RNA-seq dataset and TIMER31, we found that the expression of CD48 and KDM6A was positively correlated with intertumoral NK cell abundance in many human cancer types, suggesting that KDM6A and CD48 affect NK-mediated tumor immunity in a variety of human cancers." (PMID 38355622, 2024). "In addition, CD48, CTLA4, HHLA2, TNFSF9, and TNFSF15 were elevated in high-risk group, suggesting that the high-risk group are more likely to show immunosuppressive phenotype in tumor microenvironment." (PMID 37903974, 2023). "Therefore, up-regulation of CD48 on PBNK from ccRCC may contribute to tumor resistance to NK cell-mediated effector functions." (PMID 34149719, 2021). "To further evaluate the roles of these genes in tumor recognition and immune response, we examined the expression levels of their corresponding ligands, Ulbp1 (ligand for NKG2D) and Cd48 (ligand for 2B4/SLAMF4), on BLMP1/2A cells and T-ALL tumor cells." (PMID 40534857, 2025). "Key immune activation and tumor suppression genes including CD2, CD3, CD247 (CD3 zeta chain), CD48, CD84, CCL19, CXCL10, and SLAMF6 were consistently upregulated in the hot phenotype across all ancestries." (PMID 41387728, 2025). "E0771 primary tumor development induced an increase of BM Lin−Sca1+c-Kit+ (LSK) cells and multipotent progenitors (MPPs, CD48+CD150−)." (PMID 36976637, 2023).
tumor (continued). "The overall survival and chemotherapy response of LSCC patients have been predicted by models consisting of histopathological factors (CA199, CA724), genes (CD48, CD2), radiomics, and clinical factors (tumor differentiation, age, and stage)." (PMID 36135078, 2022). "Our data from the functional study confirmed that HCLS1, EVI2B, or CD48 suppresses CRC progression by inhibiting the proliferation, migration, and invasion capacity of CRC cells as well as tumor growth in vivo." (PMID 32426282, 2020). "The immunostaining revealed that HCLS1, EVI2B, or CD48 proteins expression were higher in pcDNA 3.3-HCLS1, pcDNA 3.3-EVI2B, or pcDNA 3.3-CD48 compared with pcDNA 3.3-NC group in xenografted tumor." (PMID 32426282, 2020). "Further, the functional study verified that over-expression of HCLS1, EVI2B, and CD48 can reduce the proliferation, migration, and invasion ability of CRC cells and significantly suppress CRC tumor growth in vivo." (PMID 32426282, 2020). "Further, our data from the functional study confirmed that the overexpression of HCLS1, EVI2B, and CD48 can reduce the ability of proliferation, migration, and invasion in CRC cells and significantly suppress CRC tumor growth in vivo." (PMID 32426282, 2020). "CD48, SEPT1, ACAP1, PPP1R16B, and IL16 were all negatively correlated with tumor purity, supporting the results for highly correlating with ICILs." (PMID 31737562, 2019). "Furthermore, CD48 contributes to immune escape by interacting with CD244 on NK cells, leading to NK cell dysfunction and reduced cytotoxicity against tumor cells." (PMID 40597436, 2025). "Additionally, MYCN-A tumors exhibited the downregulation of immune-activating genes such as CD48 and CD86, and a slight decrease in CD40 expression, potentially contributing to an immunosuppressive tumor microenvironment." (PMID 39860532, 2025). "Furthermore, lymphatic invasion—a clinical tumor characteristic—of immune genes, including CD27, CD48, and CD28, as well as infiltration of CD8+ T cells exhibited a positive and substantial connection with LCK expression (in terms of immune cells)." (PMID 37773310, 2023). "Killing assay estimating the ability of the seYTS cells to eliminate the CD48-positive tumor cells illuminated that the seYTS cells do not kill 721.221 cells more efficiently than the YTS parental control." (PMID 37609636, 2023). "Furthermore, the functional study confirmed that the overexpression of HCLS1, EVI2B, and CD48 can reduce the proliferation, migration and invasion ability of CRC cells in vitro and significantly suppress CRC tumor growth in vivo." (PMID 32426282, 2020). "This exhaustion did not occur in CD244+ NK cells co-cultured with non-tumor liver-infiltrating monocyte/macrophages, which exhibited significantly lower expression of CD48 than those from tumor." (PMID 30546369, 2018). "Further analysis of immune-stimulating factors revealed that in tumors such as LGG, PRAD, and BRCA, the expression of PLAG1 was significantly positively correlated with immune-stimulating factors like CD48, CD27, and TMIGD2, which may enhance anti-tumor immune responses." (PMID 40276502, 2025). "At present, tumor-related immunomodulators have become an important method for BC treatment, and in this study, we found that DHCR7 expression is significantly correlated with the immunoinhibitor, immunostimulators, and MHC molecules, including CD96, CD48, and HLA-DPB1." (PMID 38526324, 2024). "Interestingly, female mice that were 2B4−/− did not have any improvement in controlling tumor growth compared to their male counterparts, revealing a gender-specific role of 2B4 which was independent of CD48 expression on tumor cells." (PMID 32630303, 2020). "K562 tumor cells express ligands for receptors promoting natural cytotoxicity (Nectin-2/PVR for DNAM-1; MICA/B/UBLP1 for NKG2D), but do not express the 2B4 ligand CD48 or classical HLA-A, B, C, and non-classical HLA-E." (PMID 23508354, 2013).
cancer (48 papers, 2011 to 2025). A tumor composed of atypical neoplastic, often pleomorphic cells that invade other tissues. "High levels of TME-associated CD48 have been proposed as a potential target in cancer immunotherapy, as CD48 expression in the TME might contribute to immune regulation and tolerance." (PMID 40597436, 2025). "The positive association between CD27 and TIGIT, CD48 in the majority of cancers suggested a complete co-expressing landscape, and our data demonstrated that CD27 expression was strongly connected with various immunological checkpoints in varied immunocytes and unique T cells." (PMID 38169519, 2024). "A vaccine targeting CD244, leveraging antibodies against CD244 or its natural ligand CD48, has been developed to enhance T-cell activation, offering a novel approach against infectious diseases and cancers." (PMID 39092217, 2024). "CD48 is a ligand expressed on cancer cells that binds with its receptor 2B4 on NK cells for their activation." (PMID 38355622, 2024). "The associations of P4HA1 expression with LAG3, ICOS, CTLA4, CD48, TNFSF14, and CD27 expression were inconsistent among cancer types." (PMID 35812752, 2022). "For example, CD48, also known as B-lymphocyte activation marker, as Up target in four out of the five cancer cases." (PMID 31227749, 2019). "CD48 supports the lytic activity of cytotoxic T-lymphocyte against cancer growth." (PMID 36831458, 2023). "The results of the association between IFN-γ score and ICG indicated that the IFN-γ scores of virtually all of the different cancers that were investigated had a positive association with the expression of TIGIT, IDO1, ICOS, CD86, CTLA4, HAVCR2, PDCD1LG2, and CD48." (PMID 37646041, 2023). "Considering the downregulation of antimicrobial humoral response in cancer, we supposed the two B cell immuno‐stimulators, CD48 and TNFSF13B, could be the potential targets as well." (PMID 33694292, 2021). "Particularly, CD48, HAVCR2, LAG3, and TIGIT were identified as novel immunotherapeutic targets of several cancers, suggesting that the low-risk OS patients might benefit from their candidate inhibitors." (PMID 32908905, 2020). "Furthermore, we also determined that higher CD300LG levels, but not PTPRO, IL6ST or CD48, were associated with better overall survival in cancer patients." (PMID 38386350, 2024). "Remarkably, five genes (PDCD1LG2, CD48, IDO1, LAIR1, and PDCD1) were found to be present in both the cancer-immunity cycle inhibitors and checkpoint genes categories." (PMID 38540734, 2024). "CD2, CD48, and CD58, closely related to the immunoglobulin superfamily, are involved in T cell responses to cancer cells." (PMID 37904707, 2023). "In most cancers, CD86, TNFSF14, KLRK1, CD48, CD40LG, CD28, C10orf54, ENTPD1, CXCL12, and POLD2 are negatively correlated (p < 0.05)." (PMID 36081989, 2022). "We found that in some cancers, especially in LUAD and TGCT, FH expression was significantly correlated with multiple immune checkpoint markers, such as BTLA, TNFRSF14, LAIR1, CD48, and CD28." (PMID 34737838, 2021). "CD48, CD200 and VISTA are also downregulated in cancer samples, while CD276, LGALS9 and PVR are upregulated in cancer tissue." (PMID 33806327, 2021). "The expression levels of JUN, SFN, HSPB1, and CD47 in cancer cells and the expression levels of KLRB1, CD48, GZMK, and LY6E in CD8+ T cells were consistent with the scRNA-seq results." (PMID 33083004, 2020). "We explored them utilizing the pathway activity module of the GSCALite platform to determine whether these six genes (TYROBP, FCER1G, CD48, LST1, APOE, and APOC1) act through specific cancer pathways." (PMID 38515073, 2024). "Finally, we extracted the top 20 in-degree and top 20 out-degree genes as the hub nodes of each cancer and identified six co-owned immune feature genes (CD48, GPR65, C3AR1, CD2, CD3E and ARHGAP9) in these cancers." (PMID 35069897, 2022).
cancer (continued). "In addition, a correlation analysis between NET score and 45 immune checkpoint genes (ICGs) revealed that CD48, CD86, and LAIR1 were the most significant NET-related checkpoint genes in all cancer types." (PMID 35432310, 2022). "However, we discovered that CD48, CD86, and HAVCR2 were common factors in both cohorts, indicating a potential synergistic effect by targeting both ferroptosis pathways and immune checkpoints in cancer therapy." (PMID 40744688, 2025). "The analysis of 46 immunostimulatory genes in pan-cancer showed that HSP90B1 expression was positively correlated with CD40, CD270, PVR, MICB, ULBP1, TNFSF4, while exhibiting a negative correlation with CD48 and CD40LG in most cancers." (PMID 38243263, 2024).
infection (26 papers, 2010 to 2025). The state of being infected such as from the introduction of a foreign agent such as serum, vaccine, antigenic substance or organism. "Furthermore, the loss of LSK CD150+ CD34- CD48- Ki67- cells during infection represented a 24-fold decrease in number (from 831 ± 0.017 to only 34.62 ± 31.93 cells in total BM)." (PMID 28671989, 2017). "We first sought to explore whether infection of macrophages with MCMV resulted in a reduced recognition by CD244 due to the loss of CD48 on the cell surface." (PMID 24626474, 2014). "Two molecules, CD48 and CD11b, expressed on human B-lymphocytes have previously been shown to interact with heparan sulphate moieties, and our data implicated a role for the latter in B cell/epithelial cell interactions and transfer infection of polarized epithelial cells." (PMID 21573183, 2011). "The absolute number of CD48− HSCs halved compared to controls during the acute phase of infection (days 11 and 15 p.i.)and showed a highly variable rebound phase, with a trend to increase at day 24 p.i., although this was not statistically significant." (PMID 40141458, 2025). "Consistent with this, we detected a significant increase in the percentage of EdU+ CD48− HSCs during the acute phase of infection, which returned to control levels by day 24 p.i.." (PMID 40141458, 2025). "The surface levels of NTB-A (as a control) and CD48 were monitored 48 h post infection by flow cytometry." (PMID 37404017, 2023). "We thus infected primary CD4+ T cells with CH058 TF; treated the cells with IFN-β (or PBS) 24 h later; and then examined BST-2, NTB-A, and CD48 expression 48 h post infection by flow cytometry." (PMID 37404017, 2023). "CD48 can be downregulated by HIV+ cells during in vitro infection to escape autologous NK-cell-mediated killing." (PMID 36536105, 2023). "Infection associated receptor encoding genes include CCR1 (encoding a receptor for CCL5), CRLF2 (cytokine receptor like factor 2), IL10RA, TLR2, CD2, CD48 and IL7R." (PMID 35061738, 2022). "Strikingly, the CD148+CD48+ MKs increased rapidly after 6 h of infection and peaked at 36 h when the platelet count was the lowest." (PMID 34042332, 2021). "Other genes in this network associated with immunity and infection were toll-interleukin 1 receptor (TIR) domain containing adaptor protein, CD38 molecule, CD48 molecule, CD81 molecule, inducible T-cell co-stimulator ligand." (PMID 29302351, 2017). "Surface reductions in CD84 and Ly108 were already observed at 24 h post-infection (hpi), and at 48 hpi for CD48 and CD229, becoming for all four receptors more pronounced at 72 hpi." (PMID 24626474, 2014). "At different times (24 h, 48 h, and 72 h) after infection, cells were stained for the surface expression of CD48, CD84, CD229, and Ly108." (PMID 24626474, 2014). "Despite the increase in total numbers of LT-HSCs, the absolute number of quiescent CD48− LT-HSCs remained remarkably stable even though a greater proportion of this and other subsets were proliferating after infection." (PMID 24825601, 2014). "This decrease in CD48 occurred concomitantly with the appearance of m154, which was readily detected 48 h after infection, reaching a maximum at 72 hpi and then continuing to accumulate in the infected cell." (PMID 24626474, 2014). "CD48 (∼40 kDa band) levels were drastically lower in total cell lysates of infected macrophages, especially after 48 h of infection." (PMID 24626474, 2014). "As both CD48 and CD11b have been reported to interact with heparan sulphate, we examined CD48 expression in control and virus-loaded memory B and naïve B cells at the time (24 hours post-infection) that they were used for transfer infection." (PMID 21573183, 2011). "We observed that, at homeostasis, the LSK CD150+ CD135− population expressed low levels of CD48, but that the infection-induced LSK CD150+ CD135− cells uniformly expressed high amounts of CD48, indicating that these latter cells were unlikely true LT-HSCs." (PMID 22194881, 2011).